GAGE2A (G antigen 2A)
Synonyms: GAGE-2A; GAGE2; CT4.2; GAGE-2
Tractability: Antibody: the Human Protein Atlas places it where antibodies can reach.
Gene: Protein-coding gene on chromosome X (49,589,496 to 49,596,827, forward strand). Ensembl gene ENSG00000189064.
Subcellular location (Human Protein Atlas): Plasma membrane; Cytosol; Golgi apparatus
Homologues: Orthologues: chimpanzee GAGE10 (84% identical). Paralogues in human: GAGE12F (97% identical), GAGE12G (97% identical), GAGE13 (97% identical), GAGE12C (97% identical), GAGE12D (97% identical), GAGE12E (97% identical), GAGE1 (96% identical), GAGE12H (96% identical), GAGE12J (96% identical), GAGE10 (92% identical), GAGE2E (91% identical), PAGE1 (53% identical), and 10 more.
Diseases named in the same sentence as GAGE2A in open-access papers:
GAGE2A is named in the same sentence as 11 diseases in open-access papers, as found by Europe PMC text mining. Sharing a sentence is not in itself a finding about the gene and the disease. The quoted sentences say what the papers report.
ovarian tumors (1 paper, 2023). "For ovarian tumor samples, we detected six hub genes: GAGE2A, GAGE1, MAGEA9, CTAG1A, CTAG1B, and MAGEA1." (PMID 37835834, 2023). "A survival analysis using the Kaplan–Meier estimator showed the potential impact of GAGE2A and CT45A1 up-regulation on poor disease-free survival prognosis in ovarian tumors, which was confirmed by a multivariate survival analysis." (PMID 37835834, 2023).
cancer (4 papers, 2015 to 2024). A tumor composed of atypical neoplastic, often pleomorphic cells that invade other tissues. "Among the most significantly upregulated genes, we identified common biomarkers in human cancers: STC2, CACNA1C, and GAGE2A." (PMID 38493239, 2024).
tumor (3 papers, 2022 to 2023). "The examination indicated the hub genes in tumor samples, including GAGE2A, GAGE1, MAGEA9, CTAG1A, CTAG1B, and MAGEA1; and the hub genes in healthy ovarian tissue samples, including SPA17, MAGEC1, KDM5B, SSX4, and MAGEA9." (PMID 37835834, 2023).
GAGE2A also shares sentences with these, for which no sentence is quoted: ovarian carcinoma (3 papers); breast carcinoma (1); fibrosarcoma (1); gastric tumors (1); hepatocellular carcinoma (1); Hodgkins lymphoma (1); lung carcinoma (1); myeloma (1).